EPCAM (epithelial cell adhesion molecule)
Diseases named in the same sentence as EPCAM in open-access papers (continued):
Sharing a sentence is not in itself a finding about the gene and the disease.
cancer (continued). "Since IgG mAbs predominantly activate different immune cells, such as NK cells, it should be further evaluated whether IgA EpCAM mAbs can pose an alternative strategy against PDAC and cancer in general." (PMID 40358156, 2025). "This reduction correlated with increased expression of stem cell markers, such as PROM1, CK19, DLK1, SALL4, and EPCAM, suggesting that low SLC2A2 levels may promote cancer stem cell traits, malignancy, and therapeutic resistance." (PMID 40279337, 2025). "Nevertheless, its usage as a CTC biomarker is limited as it cannot be used for cancers lacking or expressing EpCAM, like that of neurogenic cancers, as well as CTCs with diminished EpCAM peri-EMT." (PMID 40109625, 2025). "Next, we constructed 15 EpCAM X CLDN3 bsAbs and tested their binding and internalization activity in OVCAR-3 and NCI-H1781 cancer cells to obtain bsAbs that could restore binding and internalization activities." (PMID 40057807, 2025). "Decades later, in 2009, the field achieved a major milestone with market approval of the first bispecific Ab catumaxomab (Removab) against epithelial cell adhesion molecule (EpCAM) and CD3 markers to target malignant ascites that arise from epithelial carcinoma." (PMID 41573565, 2025). "CTCs of carcinoma origin are expected to express epithelial-specific markers such as EpCAM and/or cytokeratins (CK), which are not expressed in leukocytes." (PMID 40429857, 2025). "Similarly, isolated EpCAM+ HCC cells initiated highly invasive HCC in mice and exhibited similar cancer-stem-cell-like traits." (PMID 38612911, 2024). "Next, we investigated expression of epithelial prostate (cancer) markers KRT, AR and EpCAM." (PMID 38704600, 2024). "Trispecific (CD16, IL-15, CD133) and tetraspecific (CD16, IL-15, EpCAM, CD133) NK cell engagers have also demonstrated appreciable anti-cancer efficacy against colorectal Caco-2 cells, as well as a panel of breast, prostate, HNSCC, CRC, and AML cell lines, respectively." (PMID 38612911, 2024). "For the MMR signatures, we found a significant positive correlation between them and MCM3 broadly in pan-cancer, and a negative correlation between EPCAM and MCM3 expression in LGG and THYM." (PMID 38698811, 2024). "Noticeably, those sEV-RNAs were not necessarily originated from cancer cells, since target-selecting procedures, such as anti-EpCAM-based immuno-capture, were not conducted before sEVs isolation." (PMID 39121006, 2024). "It turned out that there are cancer types that express low or no EpCAM3,4, which means that the use of EpCAM-based commercial platforms such as CELLSEARCH is extremely limited." (PMID 38806508, 2024). "Using both epithelial and mesenchymal cancer markers, as well as detection techniques that do not rely on markers, can improve the limited success of EpCAM-based technologies for isolating CTCs." (PMID 38746681, 2024). "The transcriptomic analysis confirmed mRNA expression of classical epithelial markers (cytokeratins, claudins, EpCAM, E-cadherin) in the SW480 cancer cell mono-spheroids and typical fibroblast markers (ACTA2/α-SMA, FAP-α, PDGFR, and MRC2) in the fibroblast mono-spheroids." (PMID 39011470, 2024). "We hypothesized that individuals with homozygous EPCAM deletion will exhibit a unique “tissue-specific CMMRD” and will develop hypermutation, microsatellite instability and cancers restricted to tissues in which EPCAM is expressed." (PMID 38467830, 2024). "Notably, the cancer-related genes CA9 and NDUFA4L2 and the epithelial marker genes KRT8 and EPCAM were expressed across cell states 1, 2, 3, and 5, and before the second differentiation node, marking the presence of TECs." (PMID 39301023, 2024). "In the context of the acidic microenvironment of cancer, BACE1 may cleave EpCAM at the β-site extracellularly." (PMID 38791091, 2024).
cancer (continued). "Although mild expressions were demonstrated in total cancer cell cluster C1 and C8 in non‐recurrent group, the CLDN4 expression along with ELF3, TACSTD2 and EpCAM could only be seen in recurrent cells of total C1." (PMID 38629624, 2024). "Finally, we validated the potential of ITGAV to identify hybrid/plastic cancer cells by analyzing the expression of ITGAV and EpCAM in epithelial, mixed, and mesenchymal mouse cSCCs through standard clinical methods such as IF." (PMID 39075581, 2024). "Importantly, C. sinensis infection upregulated the expression of HCC cancer stem cell markers CK19 and EpCAM." (PMID 38285640, 2024). "EpCAM is known as an adhesion molecule and a biomarker for circulating tumor cells, involved in the mediation of intercellular adhesion, proliferation, migration, stem cell characteristics, and EMT of cancer cells." (PMID 39275004, 2024). "Cancer stem cells are identified using cell surface markers and although no markers are exclusively specific to LCSCs15, we identified CD24, CD44, CD133, and EpCAM that are correlated to CAR expression." (PMID 39730609, 2024). "Furthermore, when cancer cells undergo epithelial to mesenchymal transition (EMT), thus increasing the cancer cell motility, the CTCs can lose the EpCAM marker." (PMID 38434238, 2024). "There are many markers that could differentiate CSCs from NSCs such as CD44, CD133, CD24, EpCam, ALDH1A1, etc.; these markers are highly expressed in wide types of cancer 25-27." (PMID 39513121, 2024). "The spatial domain 2 were enriched in the GO terms and KEGG pathways of cell differentiation, and included cell markers, such as EPCAM, KRT8, and CLDN3, which are connected with epithelial carcinogenesis, epithelial-mesenchymal transition (EMT) or cancer enhancement." (PMID 38972896, 2024). "Moreover, the EVs carry surface markers specific to cancer stem cells, namely, CD44, CD133, SSEA4 (stage-specific embryonic antigen-4), and CD326/EpCAM (epithelial cell adhesion molecule) that allows their identification and characterization." (PMID 39473666, 2024). "EpCAM is a direct transcriptional target gene for Wnt-β-catenin signaling in HCC cells, and is considered to be a biomarker for human epithelial tissues and malignant epithelial tumors." (PMID 39199591, 2024). "Considering the strong abundance of EpCAM in a wide variety of epithelial cancer types, EpCAM-targeted DARPin-based NIRF/PA imaging tracers may be deployed in a broad, pan-carcinoma clinical context." (PMID 37642704, 2024). "In carcinomas, epithelial cell adhesion molecule (EpCAM) is expressed at levels far higher than those of normal epithelial cells." (PMID 39618102, 2024). "This CTC detection kit is already in clinical use, but it has some limitations since EpCAM expression is absent in some cancer cells, such as those that undergo epithelial-to-mesenchymal transition." (PMID 37242756, 2023). "As we know, CTCs expressing epithelial markers (EPCAM, cytokeratin (CK)) and lacking CD45 (a leukocyte marker) have been associated with poor outcome in many cancer types." (PMID 37849806, 2023). "Epithelial cell adhesion molecule (EpCAM) is a homophilic type I transmembrane glycoprotein belonging to the small GA733 protein family, EpCAM functions not only in physiological processes but also participates in the development and progression of cancer." (PMID 37904877, 2023). "CD24, EPCAM, and CD133, the markers of cancer stem cells (CSCs) reflected the stemness." (PMID 37466793, 2023). "To investigate whether EpCAM and HGFR activation cooperatively regulates cancer cell invasion, we examined EpCAM knockout cells with or without HGF treatment." (PMID 37543570, 2023). "Moreover, claudin-low cancers display low expression of epithelial surface molecules CD24 and EpCAM and high expression of CD44 and CD49f." (PMID 37345027, 2023).
cancer (continued). "In AsPC-1 and Capan-2, the DF5 derivative induced a sharp and statistically significant reduction in the percentages of CD133+EpCAM+ cancer stem-like PC cell subpopulation, whereas RSV did not affect this subpopulation in the same PC cells." (PMID 36768301, 2023). "Catumaxomab (genetically engineered bivalent anti-EPCAM and anti-CD3 antibody) is approved for the treatment of malignant ascites and it has been also used experimentally for the treatment of bladder and ovarian cancers." (PMID 37006265, 2023). "EpCam and KRT19 were reported as prognostic cancer markers correlated with clinical outcome." (PMID 36865791, 2023). "Various epithelial markers including epithelial cell adhesion molecule (EpCAM), cadherin 1 (Cdh1), keratin (Krt) 5/14, desmoglein 2 (Dsg2), and epithelial splicing regulatory protein 1/2 (Esrp1/2) have been adopted to depict the EMT states of cancers." (PMID 37654227, 2023). "Malignant cells were identified using epithelial markers such as EPCAM and KRT18, and nonmalignant cells were annotated as myeloid immune cells, B cells, plasma cells, T cells and cancer-associated fibroblasts according to canonical markers." (PMID 36739462, 2023). "A drawback of using CTCs as diagnostic biomarkers is the possible lack of specificity, since they mainly use pan-cancer markers, such as the epithelial cell-adhesion molecule (EpCAM) and creatine kinase (CK)." (PMID 37370775, 2023). "Cancer stem cells are identified and can be isolated based on the expression of specific cell-surface proteins that act as molecular biomarkers, among which the most frequent markers are CD44, CD133, CD24, EpCAM, and LGR5." (PMID 37367867, 2023). "It is likely that such a mechanism involving not only E-cadherin but also the epithelial cell adhesion molecule (EpCAM) gene could be active in BC, and this may be a stimulus for future studies concerning the involvement of PAR5 in this cancer type." (PMID 37238229, 2023). "EpCAM, sometimes indicated as CD326, is a transmembrane glycoprotein frequently heterogeneously overexpressed in carcinomas, but not in cancers of non-epithelial origin." (PMID 36683059, 2023). "EpCAM is one of the most common CSC markers, not only in HCC but also in other cancers." (PMID 37686163, 2023). "Epithelial cell adhesion molecule (EpCAM) is extensively expressed on the surface of CTCs derived from cancer cells and has not been observed in normal blood cells." (PMID 37525780, 2023). "Regarding the evaluation of the effect of EpCAM expression on survival, in our study, we showed that tumors with high EpCAM expression had reduced disease-free survival (DFS) and overall survival (OS) (p < 0.001) compared to patients with cancers with low EpCAM expression." (PMID 37627911, 2023). "In the case of the EpCAM-negative cancer cell line (293T kidney cancer), the capture efficiency was measured at 26.14 ± 5.30%." (PMID 37754116, 2023). "In addition to the classic biomarkers, such as CD133, CD44, epithelial cell adhesion molecule (EpCAM), and CD90, other biomarkers have also been studied in specific cancers." (PMID 38164743, 2023). "In addition, AEC-CCo-CP-Fe-bLf NCs in the diet reduced the cancer markers of malignity of the Caco-2 cell (CD3133, EpCAM, and CD44)." (PMID 37259362, 2023). "We found increased expression of CK19, but not EpCAM, in THCs, parental cancer cells, and parental macrophages after the circulation." (PMID 37848444, 2023). "Regarding the evaluation of the effect of EpCAM expression on survival, in our study, we showed that tumors with high EpCAM expression had reduced disease-free survival (RFS) (p < 0.001) and overall survival (OS) (p < 0.001) compared to patients with cancers with low EpCAM expression." (PMID 37627911, 2023). "EpCAM molecules are highly expressed in epithelial cells and cancer, but it is absent in blood cells." (PMID 37754116, 2023). "Based on qRT-PCR, carcinoma featured higher levels of EpCam than non-tumorous nasopharyngeal tissues." (PMID 37108193, 2023).
cancer (continued). "This automated platform employs a ferrofluid-coupled antibody to magnetically capture CTCs derived from carcinomas through targeting the epithelial cell adhesion molecule (EpCAM) which is not expressed by blood cells." (PMID 38033786, 2023). "EpCAM is highly expressed in most epithelial cells including most carcinomas while being absent in blood cells." (PMID 36823365, 2023). "Thus, in a liquid immune suppressive microenvironment, both WT1-expressing EpCAM+ adenocarcinoma cells and WT1-CTLs reflected cancer progression." (PMID 36293034, 2022). "Although the exact implications of diffuse versus focal EpCAM expression are not certain, EpCAM has been described in the context of multiple cancers as a marker of cell ‘stemness’." (PMID 36010647, 2022). "Considering differential EpCAM expression in cancerous and normal cells, we evaluated the anti-cancer capability of prepared nanocarriers against both EpCAM positive and negative cell lines in vitro." (PMID 36686226, 2022). "This is because ANXA2 has been reported to function as a co‐receptor for tissue plasminogen activator (tPA) at the cell surface of endothelial and cancer cells, and the current study suggests the co‐localization, dependence and interaction between ANXA2 and EpCAM at the cell surface." (PMID 34240826, 2022). "However, we observed a significant diminution of epithelial cellular adhesion molecule (EpCAM) membrane expression by MFI and a lower proportion of annexin-V+ cells within HLA-I– cancer cells (respectively)." (PMID 35503263, 2022). "In addition, cluster 4 and 1 expressed cancer stem cell-like cells (CSCLCs) gene markers CD24, CD44, and EPCAM, whereas cluster 0 and 2 expressed CD44 and NOTCH2, a gene marker denoted the activation of CSCLCs." (PMID 35733218, 2022). "In addition, we analyzed the correlation pair-wise (Pearson’s correlation test), between PEBP1 (RKIP) and SNAI1, VIM, CDH1/2, EPCAM, and LAMA1/B1 genes, across the 22 different types of cancer and normal tissues in the TCGA database." (PMID 36230521, 2022). "SATB2 may be a driving force for developing cancer stem‐like phenotypes in damaged hepatocytes where induction of stem cell markers (CD44, CD90, EpCAM, AFP and LGR5) and pluripotency maintaining factors (POU5F1/Oct4, Sox‐2, Nanog and KLF4) was prominent." (PMID 35152538, 2022). "Considering the individual cancer-specific proteins, the highest number of HIV peptides homologous to TAAs (six) were predicted for the CCR9 (breast ca) and EPCAM (colon ca) proteins, covering the two most frequent HLA-A alleles in the world population (02:01 and 24:02)." (PMID 36243758, 2022). "Nevertheless, in recent years, many studies have found that EpCAM is heterogeneously expressed or even not expressed on some cancers and cancer subtypes." (PMID 35962400, 2022). "Detection of soluble EpCAM in serum/plasma of cancer patients did not correlate with any clinical-pathological characteristics." (PMID 36203609, 2022). "Cancer genomic analyses might assist with the real-time, active monitoring of neoantigen-specific CD8+ T cells during disease progression using EpCAM+ cancer cells derived from MPE." (PMID 36293034, 2022). "Cancer stem cells from either human GC cell lines or tumor tissues were isolated using cell surface markers such as CD24, CD44, CD54, CD71, CD90, CD133, Lgr5, ALDH1, EpCAM, and CXCR4." (PMID 36176765, 2022). "Other Wnt target genes include those of MMPs and VEGF, which are known to be involved in neovascularization and interact with cancer stem cell markers such as Sal-like protein 4 (SALL4), epithelial cell adhesion molecule (EpCAM), and the adhesion molecule E-cadherin." (PMID 35053606, 2022).
cancer (continued). "Furthermore, as compared with normal T cells, EpCAM-CAR-T cells induced more cytokine release (such as interferon‐γ, IL‐2, and IL‐6) and exhibited stronger apoptotic effects in cancer cells." (PMID 35414783, 2022). "Proteins used as cancer markers, such as ROR1, EpCAM, or CA72-4, were observed on the uEVs." (PMID 35740652, 2022). "EpCAM is an epithelial cell marker, rather than a cancer-specific one, but it is strongly expressed in most carcinomas including CRC." (PMID 35482170, 2022). "An in-vitro model of co-culture systems of MCF-7, HeLa, HEK-293, with THP-1 cells showed the occurrence of EpCAM positive (EpCAM+) and EpCAM negative (EpCAM−) heterogenetic cancer cell types labeled with the Quantum Dot antibody conjugates (QDAb)." (PMID 35393460, 2022). "One possibility is the direct contact of cancer cells (expressing EpCAM) with CD45+ blood cells, which may result in fusion to form CD45+EpCAM+ cells." (PMID 35711455, 2022). "Epithelial cell adhesion molecule (EPCAM), CD133, CD44, SOX2, and octamer-binding transcription factor 4 (OCT4) are well-known as liver CSC markers in human HCC and contribute to the stemness of cancer cells." (PMID 35464922, 2022). "These macrophage-derived cancer stem cells express stem-like markers (e.g., leucine-rich repeat-containing G-protein 5 [LGR5], doublecortin-like kinase 1 [DCLK1], epithelial cell adhesion molecule [EpCAM], CD44, and CD133) and markers for dedifferentiation and pluripotency." (PMID 35681791, 2022). "On the other hand, sequence analysis revealed a homozygous expression of SMAD4 P130L in EpCAM+ cancer cells, but it failed for other EpCAM-negative fractions." (PMID 36293034, 2022). "EpCAM (CD326) is found only in the basolateral membrane of epithelial tissue while overexpressed throughout the cancerous tissue membrane, making this molecule a good candidate for targeting in the treatment of cancer." (PMID 35986321, 2022). "In addition, we have shown that that the TPGS-FA/NC treatment markedly reduced the positive EpCAM/CD133 cell fraction as examined by FACS analysis, which suggested to be related with a suppressed self-renewal capability of these cancer stem-like cells." (PMID 35820920, 2022). "It uses an antibody against epithelial cell adhesion molecule (EpCAM), which is present on carcinoma cells but not on normal blood cells." (PMID 35225863, 2022). "EpCAM expresses in foetal livers, hepatic progenitor cells, carcinoma cells, etc., but not in mature hepatocytes." (PMID 36612149, 2022). "An interesting observation during this study was the altered surface expression of the cancer stem cell markers, CD44, CD133 and EpCAM between parent and cisplatin resistant NSCLC cell lines, in addition to stemness markers in ALDH1 cell fractions derived from cisplatin resistant sublines." (PMID 33550205, 2021). "Flow cytometry and immunocytochemical analysis were evaluated to diagnose cancer cells presence in serum based on the identification of epithelial cell adhesion molecule (EpCAM), cytokeratin, and nonexpression of CD45 and DAPI." (PMID 33922894, 2021). "Even though the direct link between EZH2 and EPCAM in cancer has not been reported, our results suggest a possible interaction of these two genes associated with somatic H3K4me3 signals in NSCLC." (PMID 33916417, 2021).